CD6 (CD6 molecule)
Diseases named in the same sentence as CD6 in open-access papers (continued):
Sharing a sentence is not in itself a finding about the gene and the disease.
infection (14 papers, 2012 to 2025). The state of being infected such as from the introduction of a foreign agent such as serum, vaccine, antigenic substance or organism. "Infection of CD6-deficient mice with a neurotropic murine coronavirus resulted in greater activation and expansion of CD4 T cells in the draining lymph nodes." (PMID 39679790, 2025). "Analysis of CD6 binding proteins revealed that infection-induced upregulation of Ubash3a, a negative regulator of T cell receptor (TCR) signaling, was hindered in CD6-deficient lymph nodes." (PMID 39679790, 2025). "Cd6 is involved in the formation and stabilization of T-cell contacts with antigen-presenting cells, a possible response to control the infection." (PMID 40038673, 2025). "Early-gestation infection was associated with increased levels of eight inflammatory biomarker, including TNSF14, TGF-α, EN-RAGE, and decreased IL-18 levels, while late-gestation infection was linked to elevations in 12 biomarkers, including CD5, CD6, PD-L1." (PMID 41510260, 2025). "CD5 and CD6 were the ones showing the maximum variation in expression levels in primary cells after infection." (PMID 34983375, 2022). "The frequencies of CD8+CD6+ T-cells in the blood, LN and bone marrow were significantly expanded in the chronic group compared to the pre-infection group." (PMID 31998302, 2019). "The expression levels of CD6 were significantly reduced in acutely-infected macaques compared to pre-infection levels and the PD-1 expression level was significantly elevated in the chronically-infected group compared to the acutely infected group." (PMID 30941141, 2019). "Infection of T cells with NiV was supported by internal positive staining for the NiV-N protein in the CD6+ sorted cells as analyzed by flow cytometry, and in the CD3+CD8+ sorted cells by positive staining for the non-structural C protein." (PMID 22303463, 2012). "Importantly, the infusion of soluble forms of CD5 or CD6 improve infection outcomes in a murine model of secondary cystic echinococcosis." (PMID 30500820, 2018). "Importantly, prophylactic infusion of soluble CD5 or CD6 significantly ameliorated the infection outcome in the mouse model of secondary cystic echinococcosis." (PMID 30500820, 2018). "CD6, a NA-specific mAb, protects mice against lethal challenge with the reassortant pH1N1 virus CA/09-X179A, making it an attractive antibody candidate for treating infection with pH1N1 viruses, especially those resistant to licensed NA inhibitors." (PMID 25668439, 2015). "This interaction could lead to infection of CD6+CD8+ lymphocytes by the microvascular endothelium at the point of crossing the BBB." (PMID 22303463, 2012). "We were able to narrow the infection of the CD6+ lymphocytes to CD4−CD8+ and CD4+CD8+ T lymphocytes using triple staining for NiV antigen, CD8 marker, and CD4 marker: T cells gated for CD8+ and NiV antigen staining had high percentage of cells with positive staining for CD8+ and NiV." (PMID 22303463, 2012). "Here, CD6 was quickly upregulated on LN CD8+ T-cells during acute infection and was sustained into the chronic phase of infection." (PMID 31998302, 2019). "The frequency of CD6 and PD-1 co-expressing CD8+ T-cells was significantly increased in lymphoid tissues and BAL during chronic SIV infection compared to pre-infection levels." (PMID 31998302, 2019). "However, as anticipated, the frequency of CD8+ T-cells co-expressing CD6 and PD-1 in the LN, bone marrow and BAL was significantly expanded in the chronic group compared to the pre-infection group." (PMID 31998302, 2019). "Central and effector memory CD8+ T cells are critically important in curtailing SIV disease progression following acquisition, therefore we assessed the co-expression of CD6 and PD-1 on different memory CD8+ T-cell subsets during the chronic phase of infection." (PMID 31998302, 2019).
infection (continued). "The frequencies of CD8+ T-cells co-expressing CD6 and PD-1 were not significantly different between acutely-infected and pre-infection groups in the blood, LN, bone marrow, and BAL." (PMID 31998302, 2019). "As expected, CD6 did not prevent infection, but resulted in significant reduction of lung virus titres that was proportional to the dose of mAb administered." (PMID 25668439, 2015). "Namely, CD5, CD8A, CD6 and CD244, C-C and C-X-C motif chemokines (CXCL5 CXCL6, MCP-4, and CCL20), as well as CD40, PDL-1, CUB domain-containing protein 1 (CDCP1) and interleukin-12B (IL-12B) were elevated in the late infection group compared to the unexposed group." (PMID 41510260, 2025). "To determine whether the expansion of CD8+CD6+ T cells was an outcome of chronic infection and not vaccination, we assessed the dynamics of CD8+CD6+ T cells throughout vaccination before infection." (PMID 31998302, 2019).
bacterial infection (3 papers, 2021 to 2025). "By means of CD5- and CD6-deficient mice, it has been demonstrated that both lymphocyte receptors are integral and non-redundant components of the host’s immune defence against fungal and bacterial infections." (PMID 39452619, 2024). "CD6 regulates B1a cell function and contributes to the production of natural IgM antibodies, which are critical for early immune responses against bacterial infections." (PMID 39996744, 2025). "Studies in CD5 and CD6 knockout mice showed relevant and non-redundant roles in immune defence toward fungal and bacterial infection, respectively." (PMID 39452619, 2024).
infectious disease (3 papers, 2016 to 2025). A disorder directly resulting from the presence and activity of a microbial, viral, or parasitic agent in humans. "However, despite indications that CD6 has a suppressive role in the presence of bacterial superantigens, the function of CD6 in the context of infectious disease remains understudied." (PMID 39679790, 2025). "Therefore inflammatory-disease specific eQTLs, such as the eQTL for CD5 and CD6, may be important for understanding the heterogeneity of clinical course in autoimmune and infectious diseases." (PMID 27015630, 2016).
renal disease (1 paper, 2022). "In order to examine the mechanisms underlying the improved renal disease following anti-CD6 blockade in MRL/lpr lupus mice, we examined the cellular infiltrates." (PMID 34981775, 2022). "Together, these data suggest that the CD6/ALCAM pathway plays a role in both renal disease as well as systemic disease in SLE." (PMID 34981775, 2022).
CD6 also shares sentences with these, for which no sentence is quoted: chronic graft versus host disease (4 papers); Crohn disease (3); cardiovascular disease (2); acute graft vs. host disease (1); acute myeloid leukemia (1); anemia (1); autoimmune encephalitis (1); autoimmune hepatitis (1); breast invasive carcinoma (1); breast tumor (1); calculus (1); cardioembolic stroke (1); cervical cancer (1); cervical squamous cell carcinoma (1); Cholecystitis (1); Cirrhosis (1); colorectal cancer (1); demyelinating disorder (1); encephalomyelitis (1); endocervical adenocarcinoma (1); Hashimoto thyroiditis (1); head and neck squamous cell carcinoma (1); immunodeficiency (1); inflammatory liver diseases (1); large artery stroke (1); leukemia (1); Lipedema (1); lymphoid neoplasm (1); lymphoma (1); membranoproliferative glomerulonephritis (1).
A further 17 diseases each share a sentence with CD6 in 1 paper.